NLRP3 (NLR family pyrin domain containing 3)
Diseases named in the same sentence as NLRP3 in open-access papers (continued):
Sharing a sentence is not in itself a finding about the gene and the disease.
Insulin resistance (continued). "In the adipose tissue of such individuals, especially in macrophages, the expression of the NLRP3 inflammasome components, the activity of caspase-1, and the level of IL-1β are increased, all of which are directly correlated with insulin resistance, metabolic syndrome, and the severity of T2DM." (PMID 31835423, 2019). "Therefore, the NLRP3 inflammasome-mediated inflammation play a key role in the relationship between fatty acids and metabolic diseases such as insulin resistance." (PMID 29538286, 2018). "Moreover, with the lack of NLRP3 and IL-1β, our findings revealed the improved insulin signaling cascade in vitro, suggesting the NLRP3 inflammasome as an important determiner of insulin resistance." (PMID 29096724, 2017). "Therefore, inhibition of NLRP3-induced inflammatory response and reduction of insulin resistance are of great significance in the prevention and treatment of type 2 diabetes." (PMID 28928791, 2017). "NLRP3 knockout mice were protected against insulin resistance induced by high-fat diet." (PMID 28928791, 2017). "Therefore, we focused on exploring the role and mechanism of the NLRP3 inflammasome activation in insulin resistance." (PMID 29096724, 2017). "In addition, it decreased the expression of interleukin-1β and tumor necrosis factor-α, which are the key proinflammatory cytokines involved in insulin resistance; besides, it reduced the expression of NLRP3 inflammasome." (PMID 28928791, 2017). "The results show that the insulin resistance was partially attributable to the NLRP3 inflammasome." (PMID 29096724, 2017). "Notably, searching for an effective method to attenuate NLRP3 inflammasome-mediated inflammation will be a novel advance in treatment for insulin resistance and T2D." (PMID 29096724, 2017). "Next, we studied whether the NLRP3 inflammasome-dependent IL-1β production contributed to insulin resistance." (PMID 29096724, 2017). "Our data establish that NLRP3 inflammasome-mediated increase of IL1β, TNFα and IL12-p40 in response to LPS-associated danger signals participate in the development of proinflammatory state, leading to insulin resistance." (PMID 27321128, 2016). "In addition, these mice display increased inflammation in skeletal muscle as demonstrated by higher levels of IL-1β, caspase-1 and NLRP3, probably explaining the increased insulin resistance in these mice." (PMID 26405763, 2015). "Furthermore, strong correlations between the expression of NLRP3 inflammasome-related genes and insulin resistance have been recently reported in obese male subjects with impaired glucose tolerance." (PMID 23843683, 2013). "Several studies have also shown that the NLRP3 inflammasome may play a crucial role in insulin resistance and the potential development of type 2 diabetes." (PMID 24137163, 2013). "Several studies on innate immune cells have demonstrated that the myeloid-derived NLRP3 inflammasome complex may contribute to promote inflammatory cytokine production and insulin resistance through reduction of insulin signaling." (PMID 23843683, 2013). "Interestingly, NLRP3 activation was ROS-dependent and secreted IL-1β impaired insulin signaling and promoted insulin resistance in mice." (PMID 22411934, 2012). "By comparing both fat depots, we aimed to better understand the contribution of adipose tissue inflammation to PCOS pathogenesis and to explore whether the NLRP3 inflammasome represents a mechanistic link between hyperandrogenism, adipose dysfunction, and insulin resistance in this condition." (PMID 41596350, 2026). "Based on previous studies demonstrating how NLRP3 inhibition ameliorates insulin-resistance, Liang and colleagues demonstrated that fasting improves insulin sensitivity in mice and reverses insulin resistance in vitro, specifically in adipocytes used as a cellular model of insulin resistance." (PMID 39899119, 2025).
Insulin resistance (continued). "Hyperglycemia (HbA1c>7%) activates the NLRP3 inflammasome, leading to increased IL-6 secretion from monocytes, reduced efficiency of serum albumin synthesis, and a positive correlation between the homeostasis model assessment of insulin resistance (HOMA-IR) and NLR." (PMID 40831574, 2025). "Furthermore, UA can activate the NLRP3 inflammasome, subsequently inducing the secretion of pro-inflammatory cytokines including Interleukin-1β (IL-1β), which exacerbates hepatic inflammation and insulin resistance (IR)." (PMID 41341141, 2025). "Furthermore, free fatty acids, such as cis-vaccenic acid, may lead to the generation of reactive oxygen species and act as modulators of the NLRP3 inflammasome, which may play an important role in insulin resistance." (PMID 39458502, 2024). "Therefore, we aimed to explore the effect of combined Yijinjing and resistance training on pre-diabetic subjects and determine whether the NLRP3 inflammasome correlates with the pre-diabetic symptoms insulin resistance and liver injury." (PMID 36817440, 2023). "In this study, CY-09 was used to inhibit the activation of NLRP3 inflammasome, leading to the restoration of glucose metabolism, as demonstrated by the increases in the expression and distribution of glucose transporters and related enzymes and the attenuation of insulin resistance." (PMID 36978970, 2023). "However, previous experimental and clinical studies provide evidence that XOR inhibitors have the potential to prevent the development of NAFLD, through attenuation of hepatic lipid accumulation, insulin resistance, and activation of macrophage and NLRP3 inflammasome." (PMID 36979653, 2023). "In addition, several studies using genetically modified mice that lack inflammasome components NLRP3, ASC, and Caspase-1 provided initial evidence that activation of the NLRP3 inflammasome is a key mechanism that induces metabolic inflammation and insulin resistance." (PMID 36232419, 2022). "Under a hyperglycemic environment, ROS activates the NLRP3 inflammasome in β cells, elevating caspase-1-dependent IL-1β secretion; this mediates dysfunction of β-cell insulin secretion and promotes obesity and insulin resistance, finally leading to pyroptosis and the development of T2DM." (PMID 35355717, 2022). "Moreover, NLRP3-induced IL-1β production promotes the development of insulin resistance." (PMID 36555392, 2022). "The Con-Can mice in this study showed higher body weight gain and insulin resistance, two important features of metabolic syndrome and risk factors for systemic and chronic inflammation; therefore, we examined the protein expression of NF-κB, STAT3, VCAM, NLRP3, and IL-1β in peritumor tissues." (PMID 34876963, 2021). "In addition, NLRP3 inhibition by carbenoxolone, a derivative of glycyrrhizic acid, the active ingredient of licorice, markedly reduced intracellular lipid accumulation, inflammation and insulin resistance in liver and skeletal muscle of mice under HFD." (PMID 34831246, 2021). "Taken together, our results suggest that pharmacological inhibition of the NLRP3 inflammasome enhances GLUT4myc-eGFP translocation onto the cell surface of skeletal muscles from animals with insulin resistance, which could directly improve the glucose transport in this pathological condition." (PMID 34638553, 2021). "However, Nlrp3 knockout protects mice against the development of insulin resistance." (PMID 34769018, 2021). "NLRP3 is a protein responsible for the regulation of immune inflammation, and its activation can trigger the activation of caspase-1 and the production of inflammatory mediators, ultimately leading to apoptosis of β-cells in the pancreatic islets, leading to insulin resistance." (PMID 32774321, 2020). "In addition, altering the cellular metabolic status with statins could promote insulin resistance by activating the NLRP3 inflammasome." (PMID 31174550, 2019).
Insulin resistance (continued). "In addition, in patients treated with statins, canakinumab might even be able to reduce statin-induced insulin resistance as this is thought to depend on the activation of the NLRP3 inflammasome/IL-1β pathway." (PMID 31652822, 2019). "The connection between statins, NLRP3/IL-1β, and insulin resistance remains to be characterized in depth, and many mechanistic questions are still unsolved; understanding these aspects might pave the way for new therapeutic strategies, including a combination of statins and IL-1β inhibition." (PMID 31652822, 2019). "Thus, NLRP3 inflammasome plays an important role in palmitate-induced insulin resistance." (PMID 28928791, 2017). "Importantly, UC-MSCs cocultured with HepG2 could effectively alleviate PA and LPS-induced insulin resistance by blocking the NLRP3 inflammasome activation and inflammatory agents." (PMID 29096724, 2017). "Therefore, this study showed that WMW could reduce the production of proinflammatory cytokines and alleviate palmitate-induced insulin resistance via inhibition of NLRP3 inflammasome activation in HepG2 cells." (PMID 28928791, 2017). "Consistent with a recent published study, the replacement of saturated fatty acid for monounsaturated fatty acid in high fat diet could ameliorate IL-1β-mediated adipose dysfunction and insulin resistance in mice, highlighting the special role of saturated acid in NLRP3 inflammasome activation." (PMID 28261091, 2017). "Thus, lowering Nlrp3 inflammasome activation may protect against the transition from insulin-resistance to an overt type 2 diabetic stage by mechanisms that involve protection from loss of insulin-producing beta cells." (PMID 23483669, 2013). "In non-alcoholic fatty liver disease (NAFLD) models, mangiferin mitigated liver injury, insulin resistance, and glucose intolerance by modulating glucolipid metabolism through AMPK activation and NLRP3 inflammasome inhibition." (PMID 40647096, 2025). "Immune biomarkers such as PGE and the NLRP-3 inflammasome, oxidative stress pathways, GAL-GAL-R1, and metabolic pathways including insulin resistance and PAI1 are new drug targets to prevent and treat long COVID and its physio-affective symptoms." (PMID 40048451, 2025). "Recent research has been shown that activation of the NLRP3 inflammasome in adipocytes reduces insulin-dependent glucose uptake and contributes to TNF-α-induced insulin resistance." (PMID 40583106, 2025). "There is a positive correlation between NLRP3 and LCN2 expression, underscoring the pathophysiological relevance of this axis in metabolic dysfunction and insulin resistance." (PMID 41303567, 2025). "This regional enrichment corresponds to increased immune cell infiltration and enhanced NLRP3 inflammasome activation, supporting the role of VAT as a hotspot for metaflammation and insulin resistance." (PMID 40943225, 2025). "In rats consuming a high fructose diet, hepatic activation of TLR4, NLRP3, NFκB, and JNK with the inhibition of AMPK leads to inflammation and insulin resistance." (PMID 40725208, 2025). "Studies have demonstrated a direct inhibitory effect of curcumin on NLRP3 inflammasome activation in macrophages, which can prevent HFD-induced insulin resistance and inhibit LPS-priming and NLRP3 inflammasome activation pathways in macrophages." (PMID 36895942, 2023). "Exercise intervention may inhibit the overactivation of NLRP3 inflammasome, leads to a decreased level of inflammatory cytokine IL-1β, which further fails to induce hepatic insulin resistance, thus enhancing insulin sensitivity and improving insulin resistance." (PMID 36817440, 2023). "Measures taken against the assembly and activity of the NLRP3 (nucleotide-binding oligomerization domain-like receptor family pyrin domain-containing 3) inflammasome may be a potential and novel therapy for cerebrovascular ischemic disease concomitant with insulin resistance." (PMID 36950100, 2023).
Insulin resistance (continued). "Inhibition of the NLRP3 inflammasome activation process and thus inhibition of proinflammatory cytokine release may serve as an early modulable target to improve the inflammatory cascade in patients with insulin resistance combined with ischemic cerebrovascular disease." (PMID 36950100, 2023). "Studies suggest that dietary MUFAs can reduce IL-1β-mediated adipose dysfunction and insulin resistance via preservation of AMP-activated protein kinase (AMPK) activity which, in turn, quenches NLRP3 inflammasome activation." (PMID 35276849, 2022). "It has been reported that UC-MSCs improved insulin resistance in the liver and adipose tissues of rats with T2DM by suppressing NLRP3 inflammasome-mediated inflammation." (PMID 35505375, 2022). "Further, NLRP3 can interact with thioredoxin-interacting protein (TXNIP), a protein involved in insulin resistance." (PMID 35428826, 2022). "Moreover, SAL has been shown to regulate the NLRP3 inflammasome through the TXNIP-NLRP3 pathway, providing protection against high glucose exposure, due to the accumulation of the extracellular matrix in glomerular mesangial cells or through insulin resistance in hepatocytes." (PMID 34457117, 2021). "Specific to insulin resistance observed in T2DM is the involvement of the NLR family pyrin domain containing 3 (NLRP3) inflammasome, which activates inflammatory cytokines IL-1β and IL-18 and can lead to more severe insulin resistance." (PMID 33086602, 2020). "Mice fed with a high fat diet (HFD) enriched with palmitic acid display increased mRNA levels of caspase-1, NLRP3 and IL-1β in their SVF of adipose tissues, accompanied with insulin resistance and glucose intolerance." (PMID 32545355, 2020). "The increased level of NLRP3-dependent IL-1β induces and aggravates T2DM through β cell death and insulin resistance." (PMID 32166013, 2020). "For instance, deacetylation of NLRP3 by SIRT2 reduces IL-1β production in macrophages, and hence improves aging-related inflammation and insulin resistance in rodents." (PMID 32545355, 2020). "Inhibition of NLRP3 (via glyburide or pioglitazone, the SCFA butyrate, or MCC950) prevents the development of insulin resistance and T2DM as well as PD." (PMID 31920905, 2019). "Akin to the effect of TXNIP on insulin resistance, the role of TXNIP in ischemic stroke showed exacerbated brain injury through redox imbalance and NLRP3 inflammasome activation." (PMID 31174550, 2019). "Indeed, considering that the NLRP3 inflammasome has been associated with insulin resistance development, these kinds of research studies will be useful to shed light on the potential clinical use of omega 3 PUFA both in prevention and therapy of insulin resistance." (PMID 29538286, 2018). "A recent study showed that BBR inhibited saturated fatty acid palmitate- (PA-) induced activation of NLRP3 and release of interleukin-1β (IL-1β) in macrophages by activating AMPK-dependent autophagy, thus reducing inflammation and insulin resistance." (PMID 29164155, 2017). "Functional deletion of NLRP3 and caspase-1 ameliorate HFD-induced insulin resistance and AT inflammation." (PMID 26779183, 2015). "For example, acetylation of NLRP3 is associated with aging-related chronic inflammation, and TSA may reverse aging-related inflammation as well as insulin resistance by upregulating SIRT2 and inhibiting NLRP3 activation." (PMID 41528804, 2026). "Also, Alloprevotella had a negative association with serum lipids, insulin, fasting blood glucose, homeostatic model assessment for insulin resistance (HOMA‐IR), liver TG, as well as mRNA levels of NLRP3, NF‐κB, and Caspase‐1." (PMID 40071130, 2025). "In addition to improving insulin resistance, PF protects pancreatic β-cells through anti-inflammatory and antioxidant mechanisms, modulating key pathways such as Nrf2/ARE, NF-κB, and the NLRP3 inflammasome to mitigate oxidative stress and inflammation." (PMID 40260393, 2025).
Insulin resistance (continued). "From a mechanistic perspective, the relationship between AGE intake and insulin resistance does not appear to be related to NLRP3 inflammasome activation which, in turn, is pivotal for IL-18 production." (PMID 40263184, 2025). "Similarly, deficiency in other key components of inflammasome such as ASC and NLRP3 also protects mice from HFD induced weight gain and insulin resistance." (PMID 40433411, 2025). "In a murine model of insulin-resistance induced by HFD feeding, the stimulation of bone marrow macrophages with omega-3 FAs suppressed the activation of the NLRP3 inflammasome, thereby inhibiting IL-1β secretion and resulting in improved metabolic alterations in vivo." (PMID 39083430, 2024). "In the present study, we showed that sustained transdermal delivery of verapamil via CLCMP-based patches could reduce insulin resistance and MAFLD by inhibiting the TXNIP/NLRP3 inflammasome pathway and improving autophagic degradation of protein aggregates." (PMID 36670488, 2023). "Moreover, NLRP3 inflammasome was activated in the WAT of burn patients, indicating a possible function in conciliating burn-induced insulin resistance." (PMID 36779088, 2023). "Specifically, in liver cells, insulin resistance following As exposure was shown to be mediated by increased mitochondrial ROS production, mtDNA oxidation, and PINK1-mediated mitophagy with subsequent NLRP3 inflammasome activation." (PMID 37624175, 2023). "The occurrence of the NLRP3 inflammasome in PLWH has been well studied; however, mechanisms surrounding combinational ARV usage and possible activation of inflammasomes and its linkage to insulin resistance remain limited." (PMID 37047241, 2023). "Mitochondrial dysfunction and subsequent excess ROS production promote insulin resistance by activating c-Jun N-terminal kinases (JNK) and NLR family pyrin domain containing 3 (NLRP3) inflammasome which leads to the deactivation of the IRS1/PI3K/AKT pathway and the progression of insulin resistance." (PMID 37106780, 2023). "TNFα induces mitochondrial dysfunction, oxidative stress, and insulin resistance, which activate the adipose NLRP3 inflammasome without altering IL-1β." (PMID 37876013, 2023). "Sirtuin 2 (Sirt2), a NAD-dependent protein deacetylase that participates in deacetylation of histones and other proteins, also contributes to insulin resistance and metabolic syndrome by regulating NLR family pyrin domain containing 3 (NLRP3)-mediated inflammasome activation." (PMID 36499366, 2022). "Activated NLRP3 inflammasome and downstream caspase-1 do not affect the ratio of M1/M2 in adipose tissue but promote the secretion of IL-1β and IL-18, leading to insulin resistance." (PMID 35757707, 2022). "This suggests that NAG-1 Tg mice have a negative correlation with NLRP3 inflammasomes, which play important roles in protection against insulin resistance." (PMID 34294853, 2021). "Higher rates of mitochondrial ROS production by SFAs are reported to be involved in the activation of the NLRP3 inflammasome and weakening of insulin sensitivity, thereby supporting the existence of the relationship between HFD, inflammation, and insulin resistance." (PMID 31817726, 2019). "It should not be surprising then that ω3 fatty acids prevent NLRP3 inflammasome-dependent inflammation and insulin resistance in a T2DM rodent model." (PMID 31920905, 2019). "We show that absence of REDD1 in macrophages decreases the expression of NLRP3, secretion of IL-1β and development of insulin resistance in adipocyte-macrophage coculture." (PMID 28765650, 2017). "Interestingly, Nlrp3−/− and ASC−/− mice on a HFD for one year had increased insulin levels but were still protected against insulin resistance, displaying β-cell compensatory protective mechanisms at play." (PMID 27128935, 2016). "In addition, NLRP3 KO and caspase-1 KO mice have improved HFD-induced insulin resistance and inflammation compared to WT mice." (PMID 24064574, 2013).